GBP1 (guanylate binding protein 1)
Diseases named in the same sentence as GBP1 in open-access papers (continued):
Sharing a sentence is not in itself a finding about the gene and the disease.
glioblastoma (18 papers, 2008 to 2025). The most malignant astrocytic tumor (WHO grade IV). "The increased expression level of GBP1 was associated with EGFR amplification in glioblastoma multiforme patients with poor prognosis, implying that EGFR signaling might also be required for GBP5 induction in OSCC." (PMID 34439200, 2021). "In glioblastoma, GBP1 acts as an EGFR-induced effector, enhancing tumor growth in vivo—an effect absent in vitro, suggesting reliance on stromal or immune interactions within the brain tumor microenvironment (TME)." (PMID 40564939, 2025). "In cancers such as renal, lung, ovarian, and glioblastoma, elevated GBP1 expression correlates with aggressive growth, metastasis, and resistance to therapies, marking it as an unfavorable prognostic factor." (PMID 40564939, 2025). "This pro-invasive role involves GBP1’s association with EGFR or EGFRvIII, inducing MMP1 expression in glioblastoma." (PMID 40564939, 2025). "In glioblastoma, GBP1’s EGFR-driven role marks it as a malignancy indicator, detectable near the plasma membrane or in cytoplasmic granules via immunohistochemistry, providing a reliable prognostic tool." (PMID 40564939, 2025). "The findings indicated a high prevalence of GBP1 expression in numerous tumors, such as those found in the esophageal cancer, glioblastoma, kidney clear cell carcinoma, and stomach." (PMID 37796192, 2023). "GBP-1 correlates with poor prognosis and increased invasion/metastasis in a variety of tumors with a growth factor–driven gene signature, particularly glioblastoma." (PMID 35681772, 2022). "Among these proteins we found, Guanylate-binding protein 1 (gbp1) and Pro-neuregulin-1 (nrg1) which are key players in glioblastoma progression." (PMID 34646273, 2021). "In glioblastoma and esophageal squamous cell carcinoma, GBP1 upregulation via the EGFR signaling pathway contributes to tumor proliferation and migration both in vitro and in vivo." (PMID 29115931, 2017). "GBP1 expression is controlled by EGFR in glioblastoma and esophageal squamous head and neck cancers and is important for proliferation and tumor invasion." (PMID 29115931, 2017). "This study demonstrates that increased expression of GBP1 in EGFRvIII-expressing GBMs enhances glioblastoma growth and progression." (PMID 26848767, 2016). "Functionally, we found that silencing of GBP1 inhibited EGFRvIII-driven glioblastoma cell growth in vitro and in vivo, suggesting GBP1 is a potential therapeutic target in EGFRvIII-driven tumor growth." (PMID 26848767, 2016). "In this report, we sought to determine the potential role of GBP1 in EGFRvIII-driven glioblastoma growth." (PMID 26848767, 2016). "Similar data were obtained from another independent GBP1-overexpressing glioblastoma cell line A1207." (PMID 26848767, 2016). "Given the important oncogenic role of EGFRvIII in glioblastoma and its relationship with GBP1 expression, we examined the potential role of GBP1 in glioma cell proliferation." (PMID 26848767, 2016). "Moreover, in vivo efficacy often diverges from in vitro results, as with GBP1 in glioblastoma, requiring robust preclinical models (e.g., patient-derived xenografts, organoids) to bridge the gap, assessable through comparative efficacy trials." (PMID 40564939, 2025). "GBP-1 is also downstream of EGFR signaling in glioblastomas." (PMID 35681772, 2022). "This upregulation by EGFR signaling is GBP-1-dependent and contributes to glioblastoma invasion." (PMID 35681772, 2022). "We first examined the impact of EGFRvIII expression on GBP1 expression in glioblastoma cells." (PMID 26848767, 2016). "However, silencing of GBP1 expression significantly decreased the tumor growth rate of U87-EGFRvIII cells, indicating that GBP1 is essential for EGFRvIII-mediated glioblastoma tumor growth." (PMID 26848767, 2016). "In glioblastoma, EGFR signaling induces GBP-1, which promotes cell invasion in vitro and in vivo and cell proliferation in vivo." (PMID 35681772, 2022).
glioblastoma (continued). "Moreover, GBP1 is induced by EGFR signaling and promotes invasion because it is required for the EGF-induction of MMP1 in glioblastoma." (PMID 34439200, 2021). "IFN-γ treatment of glioblastoma cells to induce GBP-1 does not induce MMP-1." (PMID 35681772, 2022). "Overexpression of GBP1 has no obvious effect on glioblastoma cell proliferation in vitro." (PMID 26848767, 2016).
COVID-19 (12 papers, 2020 to 2024). A disease caused by infection with severe acute respiratory syndrome coronavirus 2. "The missense RNA editing level of IFI30 (IFI30:chr19:18177741, p.T223A) was significantly up-regulated, whereas the GBP1 missense editing (GBP1:chr1:89057096, p.S305G) was significantly down-regulated, with the expression of both genes increased during COVID-19 vaccines." (PMID 39308856, 2024). "In addition, recoded key antiviral and immune-related proteins such as IFI30 and GBP1 recoded by missense editing was observed as an essential component of RNA editing in response to COVID-19 vaccines." (PMID 39308856, 2024). "Interestingly, the results were consistent with those in COVID-19; 27 of the IRGs were highly expressed in myeloid cells, except Icam1, Lyn, Cybb, Casp1, Gbp1, Vnn2, Socs3, Bcl2a1 and Lcn2 genes." (PMID 36817436, 2023). "In severe conditions of COVID-19, there is a high abundance of CXCL10+ and CCL2+ inflammatory macrophages that heavily express the GBP1 inflammatory gene." (PMID 38162574, 2023). "The COVID-19 dataset revealed CAMP (AUC: 0.692), LTF (AUC: 0.764), DEFA1B (AUC: 0.701), SAMD9(AUC: 0.786), GBP1(AUC: 0.757), DDX60 (AUC: 0.802), DEFA4 (AUC: 0.763), and OAS3(AUC: 0.801) that exhibited superior diagnostic capabilities." (PMID 38115996, 2023). "The CXCL10+ CCL2+ inflammatory macrophages displayed significantly higher expression of CXCL10, CXCL11, CCL2, CCL3, GBP1, and IDO1 in severe COVID-19, inflamed RA, and CD compared to the FCN1+ macrophages." (PMID 33879239, 2021). "In addition, the expression of VANGL2 presented a reverse correlation with IFITM3, ISG15, GBP1, and TRIM27, which have been reported to play important roles in antiviral immunity in the COVID-19 patients’ database." (PMID 37352355, 2023).
glioma (11 papers, 2008 to 2023). A benign or malignant brain and spinal cord tumor that arises from glial cells (astrocytes, oligodendrocytes, ependymal cells). "In contrast, we show for the first time that overexpression of GBP1 enhanced glioma growth in a mouse xenograft model and significantly reduced survival time of glioma-bearing mice." (PMID 26848767, 2016). "Altogether, these data further confirm that EGFRvIII–p38 signaling upregulates GBP1 expression in glioma cells at the transcriptional level." (PMID 26848767, 2016). "In contrast, in an orthotopic glioma mouse model GBP1 overexpression significantly promotes glioma growth and reduces survival rate of glioma-bearing mice by increasing cell proliferation and decreasing cell apoptosis in tumor." (PMID 26848767, 2016). "We propose that GBP1 could enhance glioma growth in vivo through indirect mechanisms." (PMID 26848767, 2016). "However, forced expression of GBP1 promotes glioma growth in mice, and it may act through increasing tumor cell proliferation and reducing cell apoptosis." (PMID 26848767, 2016). "The induction of GBP1 is essential for EGFR-mediated matrix metallopeptidase-1 (MMP1) expression and glioma cell invasion in vitro and in vivo." (PMID 26848767, 2016). "More metastasis biomarkers such as TGM2, GBP1 and IGFBP7 were checked too, and all of their expressions have a positive correlation with the expression in CAV1 in all different types of gliomas." (PMID 37642765, 2023). "Overexpression of GBP1 protein appeared in tumor tissues of bladder urothelial carcinoma (BLCA), cervical and endocervical cancers (CESC), cholangiocarcinoma (CHOL), lymphoma, glioma, LIHC, LUSC, PAAD, and STAD, while the converse appeared in colon adenocarcinoma (COAD) and THCA." (PMID 35222540, 2022). "Unlike GBP1, GBP2-promoted glioma cell invasion mainly through induction of FN121." (PMID 33608513, 2021).
colon cancer (9 papers, 2011 to 2022). "Because up-regulation of GBP-1 expression in humans has been associated with longer survival in colon cancer patients, GBP-1 is considered to be an activation marker of endothelial cells during inflammatory diseases." (PMID 22254125, 2011). "Because Sep15 deficiency in mouse colon cancer cells as well as in Sep15 knockout mice in vivo demonstrated a highly increased expression of GBP-1 compared to controls, mRNA expression of GBP-1 was also evaluated in human colon cancer cells." (PMID 22254125, 2011). "Within the context of an IFN-γ-driven gene signature, GBP-1 promotes a better prognosis in breast and colon cancer." (PMID 35681772, 2022). "For example, GBP1 expression was downregulated and acts as a tumor suppressor in colon cancer." (PMID 34439200, 2021). "GBP1 suppressor role in colon cancer was also reported and reviewed." (PMID 31998647, 2019). "Additionally, quantitative RT-PCR was utilized to examine GBP-1 mRNA levels in our established murine CT-26 colon cancer cell line, in which Sep15 was down-regulated using RNAi technology." (PMID 23226526, 2012). "To elucidate this possible functional link, we are also using human and mouse colon cancer cell lines to investigate whether any, and which, regulatory elements in the promoter region of GBP-1 may be affected by Sep15 expression." (PMID 23226526, 2012). "Unlike in mouse colon cancer CT26 cells, no statistically significant increase of GBP-1 mRNA was observed in human colon cancer shSep15 cells compared to their respective controls." (PMID 22254125, 2011). "This up-regulation of GBP-1, in absence of Sep15 expression, has also been found in the mouse colon cancer cell line CT26." (PMID 22254125, 2011).
melanoma (9 papers, 2014 to 2026). A malignant, usually aggressive tumor composed of atypical, neoplastic melanocytes. "In melanoma, high GBP1 levels correlate with better outcomes, linked to heightened immune surveillance and interferon-gamma-induced T cell infiltration, reflecting its role as an immune-activated gene." (PMID 40564939, 2025). "In a melanoma dataset, GBP1 was rarely expressed in tumor cells, whereas it was comparably enriched in macrophages, as well as CD8+ T, CD4+ T, NK, and endothelial cells." (PMID 38758367, 2024). "To determine the specific cell type expressing GBP1 that contributes to immunotherapy-responsive tumors, we collected published single-cell RNA sequencing data from patients with melanoma and NSCLC." (PMID 38758367, 2024). "The expression of GBP1 showed a downward trend with the increase of total melanoma stage and T stage (P < 0.01)." (PMID 33194692, 2020). "To identify cell types expressing GBP1, we conducted a pan-cancer analysis, including melanoma and NSCLC, to evaluate GBP1 expression in 25 immune cell types." (PMID 38758367, 2024). "The expression of GBP1 decreased with the increase of tumor depth (P < 0.0001), and the expression of PRADC1 was the highest in thick melanoma subgroup (P = 0.037)." (PMID 33194692, 2020). "The gray scale quantification of these images showed that the expression of FKBP4 and RCC1 was significantly upregulated in melanoma, while the expression of PRADC1 was slightly upregulated, and the expression of GBP1 was downregulated (P < 0.05)." (PMID 33194692, 2020). "In other studies, the GBP1/2 genes are induced by type I IFN in blood cells both in vitro and in vivo in IFN treated hepatitis C and melanoma patients." (PMID 25405351, 2014). "These 13 mRNAs were further analyzed by multivariate COX proportional hazard regression analysis, and finally, four hub mRNAs that could be used to predict melanoma prognosis were selected: PRADC1, FKBP4, RCC1, and GBP1." (PMID 33194692, 2020). "The expression of GBP1 in melanoma samples with ulcers was lower than that in the non-ulcer group (P = 0.0016)." (PMID 33194692, 2020). "Studies have shown that melanoma patients with high expression of GBP family, including GBP1, have a good prognosis in the 30-year follow-uperiod, which is consistent with the result in this study that the decline in GBP1 expression predicts poor prognosis of patients." (PMID 33194692, 2020).
triple-negative breast carcinoma (9 papers, 2017 to 2025). An invasive breast carcinoma which is negative for expression of estrogen receptor (ER), progesterone receptor (PR), and human epidermal growth factor receptor 2 (HER2). "An open sea differentially methylated region (DMR) in the 5′UTR of GBP1 was found to be hypomethylated in triple-negative breast cancer (TNBC) samples." (PMID 34194003, 2021). "In addition, GBP1 is involved in cell proliferation in triple-negative breast cancer, consistent with our results." (PMID 40018406, 2025). "Knock-down of GBP1 reduces the growth of Triple-negative breast cancer (TNBC) cells." (PMID 38072995, 2023). "A differently methylated region was found in the region of the 5′UTR of the GBP1 gene (Interferon-induced Guanylate-Binding Protein 1), which was hypomethylated in triple-negative breast cancer samples compared to normal samples, which is similar to our findings in oral and oropharyngeal cancers." (PMID 37175405, 2023).
influenza (8 papers, 2011 to 2022). An acute viral infection of the respiratory tract, occurring in isolated cases, in epidemics, or in pandemics; it is caused by serologically different strains of viruses (influenzaviruses) designated A, B, and C, has a 3-day incubation period, and usually lasts for 3 to 10 days. "A number of those genes have been shown previously to play a protective role during the influenza infection (e.g. Isg20, Isg15, Gbp1, etc.)." (PMID 24073225, 2013). "One of the key regulators in this host module, GBP1, was upregulated during influenza infection." (PMID 32178738, 2020). "Human GBP1 has been shown to contribute to anti-viral activity against vesicular stomatitis virus and encephalomyocarditis virus and hepatitis C, and recent studies implicate hGBP3 in resistance to influenza." (PMID 23633952, 2013). "The role of porcine GBPs in the influenza virus replication is in process of our research, but the experiment results achieved so far could imply that GBP1 has a significant anti-viral effect for influenza (unpublished data)." (PMID 21819625, 2011). "Previous studies have shown that GBP1 and GBP3 possess anti-influenza viral activity, killing and transporting antimicrobial peptides to phagolysosomes by oxidation." (PMID 36147849, 2022). "In influenza patients, the interferon pathway-related genes IFI44, IFI6, IFIH1, STAT1, and GBP1 also showed overexpression, while no obvious interferon transcriptional signature was observed in AECOPD and CAP." (PMID 36059536, 2022).
prostate carcinoma (8 papers, 2007 to 2023). A carcinoma that arises from epithelial cells of the prostate gland. "However, it was indicated by big data analysis that GBP1 could be associated with better survival in prostate cancer." (PMID 31998647, 2019). "Conversely, reduced expression was observed in kidney chromophobe, prostate cancer, and endometrioid cancer, underscoring the importance of GBP1 as a key biomarker across a wide range of cancers." (PMID 37796192, 2023). "The knockdown of GBP1 inhibits xenograft growth and the protein expression level of EGFR is decreased in GBP1-knockout xenograft tumors in prostate cancer." (PMID 34439200, 2021). "In summary, our current study has demonstrated a pro-survival or oncogenic role of GBP1 in two independent prostate cancer lines by application of CRISR/Cas9 gene knock out technology." (PMID 31998647, 2019). "In a series of in vitro studies, the GBP1 KO prostate cancer cells were significantly sensitive to both docetaxel and paclitaxel." (PMID 31998647, 2019). "Taxane drugs are commonly used chemotherapeutic agents to treat prostate cancer patients and some previous studies reported the positive correlation between GBP1 gene expression and docetaxel/paclitaxel resistance." (PMID 31998647, 2019). "GBP1 came to our research focus only after we systemically treated the prostate cancer cell line DU145 with ethidium bromide and flavopiridol for a long period and studied the molecular mechanism behind how those cells survived such treatments." (PMID 31998647, 2019). "In this study, possible role of GBP1 in two independent prostate cancer lines by application of CRISR/Cas9 gene knockout (KO) technology was investigated." (PMID 31998647, 2019). "In the current study, we treated the DU145 and PC3 prostate cancer cells with 4 μM NSC756093 to further study the function of GBP1 in regulation tumor cell proliferation, migration and drug resistance after initial dose optimization." (PMID 31998647, 2019). "The GBP1 protein is also involved in resistance to docetaxelis of prostate cancer, and in a recent study, it was shown that it is one of the key molecules contributing to cancer radioresistance." (PMID 29350274, 2018). "The GBP1 KO prostate cancer cells grew significantly slower both in vitro and in xenograft models." (PMID 31998647, 2019). "This attempted us to explore the possible role of GBP1 in prostate cancer in this study." (PMID 31998647, 2019). "Furthermore, GBP1 protein expression in clinical prostate cancer sample revealed its aggressive clinical feature correlation and shorter overall survival association." (PMID 31998647, 2019). "Collectively, our results indicate a pro-survival or oncogenic role of GBP1 in prostate cancer." (PMID 31998647, 2019). "Furthermore, clinical prostate cancer sample GBP1 protein expression revealed its aggressive clinical feature correlation and shorter overall survival association." (PMID 31998647, 2019). "GBP1 is an IFN-α–induced transcript that is involved in immune response in prostate cancer." (PMID 31029062, 2019). "Therefore, we decided to study the GBP1 protein expression and its clinicopathological correlation in a series of prostate cancer samples, and then further explore its molecular biological consequences by performing GBP1 gene knockout (KO) in prostate cancer cell lines DU145 and PC3." (PMID 31998647, 2019). "The GBP1 gene KO DU145 and PC3 prostate cancer cells were significantly less aggressive in vitro, with less proliferation, migration, wound healing, and colony formation capabilities, in addition to a significantly lower level of mitochondrial oxidative phosphorylation and glycolysis." (PMID 31998647, 2019).